BRCA2 (BRCA2 DNA repair associated)
Diseases named in the same sentence as BRCA2 in open-access papers (continued):
Sharing a sentence is not in itself a finding about the gene and the disease.
breast cancer (continued). "The estimated lifetime risk of acquiring breast cancer with an ATM, CHEK2, PALB2 mutation is greater than 20% which is considered a “moderate risk” compared to the effects of the pathogenic variants in BRCA1 and BRCA2 genes with a lifetime risk of approximately 50%." (PMID 37239898, 2023). "Furthermore, breast cancer patients with BRCA1/BRCA2-deficiency have recently been shown to benefit from PARP inhibitor treatment which is well-known in ovarian cancer, where BRCA1/BRCA2 mutational status is routinely used for directing this treatment." (PMID 37316882, 2023). "The founder BRCA2 c.8756delG PTV was detected in 1.01% of breast cancer cases (n = 10/990) and 0.09% of controls (n = 1/1,094) which corresponds to more than half of the BRCA2 PTVs observed among cases (55.56%, n = 10/18) and the only BRCA2 PTV identified among controls." (PMID 37790698, 2023). "Vitamin supplement use is very popular among Canadian women, but the extent to which consuming vitamin D supplements may affect breast cancer risk in BRCA1 or BRCA2 mutation carriers is not known." (PMID 37345127, 2023). "Interestingly, high tumor grade did neither correlate with a worse prognosis in young breast cancer patients nor in BRCA2 mutation carriers." (PMID 38036573, 2023). "Therefore, some studies suggested that Chinese women should receive breast cancer prevention knowledge education, especially those who are at high risk of carrying BRCA1 or BRCA2 germline mutations, as studies have shown that BRCA1/2 mutations can lead to hereditary breast cancer." (PMID 36613148, 2023). "○ Women with a pathogenic mutation of the BRCA2 gene or other genes at moderate or high risk for breast cancer, in addition to those not tested, but with first-degree relatives who are carriers should undergo MRI annually from the diagnosis of the mutation (not before age 30) (Category A)." (PMID 37683660, 2023). "Women with hereditary breast and ovarian cancer syndrome have an increased risk of developing cancer, mainly breast cancer (BC)—absolute risk > 60% for BRCA1/2 carriers—and ovarian cancer (OC)—absolute risk of 39–58% for BRCA1 and 13–29% for BRCA2 carriers." (PMID 37754482, 2023). "In addition to double-strand break repair, BRCA2 (breast cancer 2) is also closely related to homologous recombination repair, while PARP-1 (poly (ADP-ribose) polymerase 1) plays important regulatory roles in single-strand break repair and basic cleavage repair." (PMID 38006403, 2023). "The exact cause of BC is unknown, but several factors can increase the risk of developing it, including age, family history of breast cancer, inherited gene mutations (such as BRCA1 and BRCA2), obesity, hormonal imbalances, and exposure to certain environmental factors." (PMID 37509426, 2023). "In addition to the best-known pair of genes that can predispose a patient to the development of breast cancer, namely the BRCA1 and BRCA2 genes, there are other genes with variable penetrance that can in some way increase the predisposition to this type of neoplasm." (PMID 36835955, 2023). "BRCA1 mutations are linked preferentially to the triple negative form of BC (estrogen receptor negative, progesterone receptor negative, and HER2 negative, TNBC), whereas BRCA2-associated breast cancers are generally estrogen receptor-positive, and phenotypically different (mostly luminal-like BC)." (PMID 36902416, 2023). "The relative risk for breast cancer and ovarian cancer is 5.9 (95% confidence interval (CI): 5.3–6.7) and 11.8 (95% CI: 10.0–14.0) for BRCA1 mutant carriers, respectively, and 3.3 (95% CI: 3.0–3.7) and 5.3 (95% CI: 4.4–6.3) for BRCA2 mutant carriers, respectively." (PMID 35163129, 2022).
breast cancer (continued). "Therefore, the frequency of BRCA2 PV carriers among women with breast cancer might have been underestimated, because the family history of breast and ovarian cancer is less marked, and breast or ovarian cancers are less penetrant or delayed in lifetime." (PMID 35158866, 2022). "In addition, the last V5 version of BOADICEA incorporates the effects of pathogenic variants (PVs), not only in BRCA1 and BRCA2 genes, but also in PALB2, CHEK2, ATM and BARD1 for the breast cancer model and RAD51D, RAD51C and BRIP1 for the ovarian cancer model." (PMID 35886069, 2022). "However, the frequency of ER and PR positivity in BRCA2 PVs is similar to sporadic breast cancer." (PMID 36518309, 2022). "Hereditary breast cancer accounts for 30% of newly diagnosed breast cancer (BC) cases and is linked with germline pathogenic variants in the high-risk genes BRCA1 or BRCA2 in approximately 24% of cases." (PMID 35329227, 2022). "However, for BRCA2, family history of breast cancer was broadly enriched in 5 cancer types." (PMID 35420638, 2022). "Finally, the well-known triple-negative phenotype of BRCA1 tumors could also result in more referrals for genetic testing for BRCA1 versus BRCA2 breast cancer patients." (PMID 35805038, 2022). "However, little is known about the relationship between iNOS and BRCA2 in breast cancer cell lines." (PMID 35740092, 2022). "Whether or not the loss of 13q11 has any BRCA2-regulatory functionality is unknown, although deletions in 13q and 14q are common in BRCA2-mutated breast cancers." (PMID 35992833, 2022). "However, RRBM-RRBSO or just RRBSO was the most effective risk-reducing strategy in patients with TN breast cancer aged over 40 years with the BRCA1 pathogenic variant in exons 12-24 in stage II and in patients aged over 35 years with the BRCA2 pathogenic variant in exons 12-24 in stage II." (PMID 36580360, 2022). "In contrast, BRCA2‐associated breast cancers are not well‐defined overall." (PMID 35128817, 2022). "However, several of our premenopausal breast cancer patients carried germline variants of unknown/uncertain significance (VUSs) in eight different breast cancer susceptibility genes, namely BRCA1, BRCA2, CHEK2, RAD51C, RAD51D, ATM, BRIP1, and PMS2." (PMID 36011273, 2022). "Among the five samples with MMR loss for which PD-L1 was available, one (20%) had detectable PD-L1 ≥1; one of the three cyclin-dependent kinases 12 (CDK12) altered samples also had detectable PD-L1 ≥1 (33%), but none (0%) of the six breast cancer 2 (BRCA2) mutated mCRPC cases expressed PD-L1." (PMID 35491356, 2022). "Patients with heterozygous germline mutations of the BRCA1 or BRCA2 genes (for example, c.5266dupC, c.1961del, c.3700_3704del, c.3756_3759del, c.4035del in BRCA1, c.5946del in BRCA2, etc.)have an increased risk of developing breast cancer (BC), as well as ovarian and other cancers." (PMID 36613648, 2022). "However, a growing body of evidence indicates that BRCA1 and BRCA2 TN as well as luminal cancers are more chemosensitive and achieve higher pathologic complete response (pCR) rates compared with breast cancer without the BRCA1 or BRCA2 pathogenic variant." (PMID 36580360, 2022). "In this study, it was found that 149 women (18.4%) developed contralateral breast cancer and that the risk of development considering a period of 15 years after diagnosis was 36.1% for carriers of mutations in the BRCA1 gene and 28.5% for women with BRCA2 gene mutations." (PMID 35805026, 2022). "Analysing mutations with correct and reliable genetic testing in the significant genes (BRCA1 and BRCA2) and less commonly mutated genes (such as PTEN) and subsequent genetic counselling in high‐risk women can be beneficial in the early detection and/or prevention of breast cancer development." (PMID 35762299, 2022).
breast cancer (continued). "Interestingly, the index cases were negative for BRCA1 and BRCA2 mutations, highlighting that this mutation in familial predisposition to breast cancer is sufficient to cause the disease on its own." (PMID 35650591, 2022). "We also observed that breast cancer patients exposed to pesticides had a higher mutational burden when diagnosed before 50 years old (p = 0.00978) and/or when carrying BRCA1 (p = 0.0138), BRCA2 (p = 0.0366), and/or PALB2 (p = 0.00058) variants, a result not found in the unexposed group." (PMID 35875117, 2022). "Thus, BRCA1 and BRCA2 are the most common germline mutated genes, while PIK3CA is the second most common somatic mutated gene in breast cancer patients; however, subtle frequency differences may be related to the age of onset of the disease." (PMID 34287479, 2021). "The K3326X mutation was associated with increased risk of breast cancer (OR = 1.28, 95% CI = 1.17 to 1.40) independent of additional BRCA2 mutations and demonstrated strong association with serous ovarian cancer (OR = 1.46, 95% CI = 1.2 to 1.70), but not with prostate cancer." (PMID 34356066, 2021). "Additionally, variants of unknown/uncertain significance (VUS) in breast cancer susceptibility genes CHEK2, BRCA2 and BRIP1 were determined to be present in three different PABC patients (15%)." (PMID 34011307, 2021). "It is possible, even if it has never been proved, that BRCA2 mutation carriers harbor more pre-malignant estrogen receptor-positive lesions and that repeated pregnancies might increase the risk of developing breast cancer." (PMID 34503502, 2021). "Furthermore, some missense variants may exhibit partially reduced activity sufficient to confer a moderately increased risk of breast cancer, as shown for R1699N substitution in BRCA1 or Y3035S in BRCA2." (PMID 34359619, 2021). "Risk-reducing salpingo-oophorectomy is associated with a 96% reduction in the risk of tubo-ovarian cancer; and may be associated with a reduction in breast cancer risk in the carriers of BRCA2, but not BRCA1, variants." (PMID 34771713, 2021). "Furthermore, with the discovery of two major breast cancer susceptibility genes, BRCA1 and BRCA2, in 1994 and 1995, respectively, the association between family history and the presence of inherited genetic events that predispose individuals to breast cancer development was confirmed." (PMID 34573353, 2021). "In addition, mutations in BRCA1 are associated with the more aggressive, receptor-negative phenotype, whereas BRCA2 mutated breast cancers are predominantly hormone-sensitive." (PMID 34441794, 2021). "BRCA1 and BRCA2 mutations are not uncommon in breast cancer patients." (PMID 34290354, 2021). "While curing breast cancer during pregnancy would be challenging, the use of PARP inhibitors has garnered much enthusiasm, and several such agents have been approved by the FDA for the treatment of patients with ovarian and breast cancers harboring inherited BRCA1 and/or BRCA2 mutations." (PMID 33854442, 2021). "This study identified putative pathogenic variants in ATM, BRCA1, BRCA2, CHEK2, and PALB2 as the most prominent genes for breast cancer, harboring protein-truncating variants that confer significant disease risks (odds ratio of 2.10 to 10.57) to overall breast cancer risk." (PMID 34439109, 2021). "In addition, a prospective multicenter cohort study reported that RRSO significantly reduced the risk of breast cancer for BRCA2 pathogenic variant carriers but not for BRCA1 carriers." (PMID 34071148, 2021). "In gene panel sequencing for breast cancer predisposition, CHEK2 is consistently found to have a high number of pathogenic variants, usually only surpassed by the number of pathogenic variants identified in BRCA1 and BRCA2 in most settings not involving selection by breast cancer subtype." (PMID 33803639, 2021).
breast cancer (continued). "To explore whether small-molecule inhibitors can sensitize cancer cells to PARPi, we performed a drug combination screen in BRCA1-deficient breast cancer cell line of HCC1937 and BRCA2-deficient CRC cell line of HCT-15, which express mutant-type BRCA1 or BRCA2 protein but modestly respond to PARPi." (PMID 33589588, 2021). "Thus, some authors have suggested that CHD4 depletion (via low CHD4 mRNA expression) might modulate the response to cisplatin in ovarian and BRCA2 breast cancers." (PMID 33981601, 2021). "Our findings are consistent with previous work in this setting and illustrate that, in contrast to pathogenic variants in BRCA1 and BRCA2 which are less prevalent in women diagnosed at older ages, the prevalence of pathogenic variants in other breast cancer genes is independent of age at diagnosis." (PMID 34887416, 2021). "This incidence was much lower than that reported in Chinese HBOC, in which 5.74 % of breast cancer and 21.79 % of ovarian cancer patients had BRCA1/2 germline mutations, with an overall pathogenic mutation frequency of 69.9 % and 71.1 % for BRCA1 and BRCA2 exons, respectively." (PMID 33563323, 2021). "In the present study, we attempted to determine the prevalence of pathogenic or likely pathogenic variants of BRCA1 or BRCA2 among the selected group of patients with breast cancer (not diagnosed as mutation carriers with the standard screening procedure in 2003–2015)." (PMID 33918338, 2021). "RRSO (risk reducing salpingo-oophorectomy) may have possibly reduced the risk of breast cancer for BRCA2 pathogenic variant carriers but not for BRCA1 carriers." (PMID 34071148, 2021). "In terms of clinicopathological features, as shown in prior studies, the majority of breast cancer cases associated with germline BRCA1 pathogenic variants were hormone receptor-negative tumors (76%) while those arising in BRCA2-mutated patients were hormone receptor-positive (83%)." (PMID 33579978, 2021). "However, recent clinical trials have indicated that a larger number of patients with breast cancer may be sensitive to PARP inhibitors because of other DNA-repair gene mutations, DNA-repair deficiency, and somatic BRCA1 and BRCA2 mutations." (PMID 34203351, 2021). "However, in France, women presenting with these mutations are not included in the organized nationwide screening and, as explained in PROCAS12, mutations in breast cancer genes such as BRCA1 and BRCA2 are too infrequent to affect risk prediction appreciably in the models for the general population." (PMID 34580360, 2021). "Compared with White women, Nigerian women with breast cancer have different epidemiological and genetic risk factor profiles, such as younger age at diagnosis, later age at menarche, higher parity, and a relatively high germline mutation rate in BRCA1 and BRCA2 genes." (PMID 34836952, 2021). "However, how the various cells residing in the TME of germline BRCA1/BRCA2-deficient breast tumors that are equally impaired by the same germline mutation contribute to the pathogenesis of the hereditary breast cancer has not been consistently addressed." (PMID 33540843, 2021). "Third, TNBC rather than some other tumor subtype as a patient’s first breast cancer diagnosis may be more strongly associated with BRCA2 and PALB2 among AA patients than among EA patients." (PMID 33479248, 2021). "Furthermore, a study of patients with ovarian cancer showed that the presence of BRCA2 PVs in the ovarian cancer cluster region was associated with a better RFS than those in breast cancer cluster regions and not-related risk regions." (PMID 35875314, 2021). "The decreased risk of breast cancer in SLE patients has been intriguing in light of mechanistic data suggesting that cell-penetrating dsDNA antibodies may have anti-cancer effects in cells with DNA repair defects, such as BRCA2-deficient human cancer cells." (PMID 33632283, 2021).
breast cancer (continued). "Moreover, combined GSK3 and PARP inhibition has yielded encouraging results in BRCA2 deficient or HR proficient colon cancer cells but not on BRCA1 deficient breast cancer HCC1937 cells." (PMID 33589588, 2021). "Besides, a metanalysis by Barretta and colleagues, including 105,220 breast cancer patients from 60 studies, showed worse OS and worse breast cancer specific survival (BCSS) in BRCA1 mutation carriers while BRCA2 carriers had worse BCSS only in comparison to sporadic cases." (PMID 34206661, 2021). "However, other attributes of the ABCFS participants and the nature of the breast cancer risks associated with pathogenic variants in genes other than BRCA1 and BRCA2 may partially provide an explanation." (PMID 34887416, 2021). "Women with germline BRCA1/BRCA2 PVs have a cumulative risk by age 80 of 17–44% for developing EOC and 69–72% for developing breast cancer (BC)." (PMID 34503154, 2021). "The BRCA2 mutant case and the four other cases showing HRD-like SNV and indel patterns also showed the presence of the rearrangement signatures associated with BRCA1/2 deficiency, although to a lesser extent than that seen in TCGA-64-1680 and in BRCA1/2 mutant breast cancer in general." (PMID 34145376, 2021). "Two breast cancer patients including the proband, her elder sister III:3 and another five women (the proband's mother, three sisters and one niece) in this family whom appeared to be normal through August 2019 also carried this heterozygous, missense mutation of BRCA2: c.7007G>T." (PMID 31782247, 2020). "The present review aims to investigate the current knowledge about BRCA2 mutations in canine cancer and the consequence of identified polymorphisms on the interaction with RAD51 protein and discuss the potential of applying synthetic lethality in the treatment of canine mammary tumors." (PMID 32005245, 2020). "Breast cancer with BRCA1 (but not BRCA2) mutations is known to typically have a basal phenotype." (PMID 32766142, 2020). "It is plausible that oophorectomy may reduce breast cancer risk in BRCA2 mutation carriers but not in BRCA1 mutation carriers." (PMID 31948486, 2020). "Since p38α inhibition increases DNA damage and chromosome instability in breast cancer and THZ1-regulated DNA homologous recombination repair associated genes such as BRCA1 and BRCA2, the role of DNA damage in antitumor effects of THZ1 may need further exploration." (PMID 32690037, 2020). "BRCA1 and BRCA2 mutations have also been reported in CVDs, for example, mutations in BRCA1 and BRCA2 are shown to be associated with a two‐fold increased risk for diabetes and a 37% increase of all‐cause mortality risk for breast cancer patients mainly due to CVDs (Zhou, Zhang, Gu, & Xia, 2015)." (PMID 32638521, 2020). "The increased risks of breast cancer with IRRs 1.5–1.7 in the age group 30–69 years and pancreatic cancer with an IRR of 2.2 after age 70 support the suggestion of disease-predisposing variants in BRCA2, causing the observed malignancies in a small subset of FCCTX families." (PMID 32321466, 2020). "In addition, consistent with the previous studies that linked the genes underlying the HRD to Signature 3 in breast cancer, the subnetworks identified for Signature 3 C/D contain BRCA1 and BRCA2 genes, two important genes in HR-mediated double-strand break (DSB) repair." (PMID 32471470, 2020).